WRNIP1 (WRN helicase interacting protein 1)
Description:
Functions as a modulator of initiation or reinitiation events during DNA polymerase delta-mediated DNA synthesis. In the presence of ATP, stimulation of DNA polymerase delta-mediated DNA synthesis is decreased. Also plays a role in the innate immune defense against viruses. Stabilizes the RIGI dsRNA interaction and promotes RIGI 'Lys-63'-linked polyubiquitination. In turn, RIGI transmits the signal through mitochondrial MAVS.
Synonyms: WHIP; FLJ22526; bA420G6.2; FAP93; CFAP93
Tractability: PROTAC: UniProt records ubiquitination sites on it; ubiquitination databases record sites on it; its protein half-life has been measured.
Gene: Protein-coding gene on chromosome 6 (2,765,393 to 2,786,952, forward strand). Ensembl gene ENSG00000124535.
Subcellular location: Nucleus; Cytoplasm
Subcellular location (Human Protein Atlas): Nucleoplasm
Gene Ontology:
Molecular function: ATP hydrolysis activity; identical protein binding; protein binding; enzyme activator activity; single-stranded DNA helicase activity; ATP binding; DNA binding
Biological process: DNA synthesis involved in DNA repair; regulation of DNA-templated DNA replication initiation; DNA-templated DNA replication; DNA damage response; DNA repair; DNA replication
Cellular component: chromosome, telomeric region; cytoplasm; membrane; nucleus; perinuclear region of cytoplasm
Genetic constraint (gnomAD): Loss-of-function variants: 40 observed, 48 expected, observed/expected ratio (o/e) 0.83, 90% interval 0.65 to 1.09. The synonymous counts are far from expectation, so gnomAD's model fits this gene poorly and the ratio says little. Missense variants: 1,113 observed, 810.69 expected, observed/expected ratio (o/e) 1.37, 90% interval 1.31 to 1.44. Synonymous variants: 520 observed, 357.07 expected, observed/expected ratio (o/e) 1.46, 90% interval 1.36 to 1.57.
Homologues: Orthologues: chimpanzee WRNIP1 (100% identical), macaque WRNIP1 (99% identical), mouse Wrnip1 (95% identical), rat Wrnip1 (95% identical), dog WRNIP1 (92% identical), pig WRNIP1 (87% identical), guinea pig WRNIP1 (81% identical), rabbit WRNIP1 (65% identical), tropical clawed frog wrnip1 (53% identical), zebrafish wrnip1 (52% identical).
Diseases named in the same sentence as WRNIP1 in open-access papers:
WRNIP1 is named in the same sentence as 9 diseases in open-access papers, as found by Europe PMC text mining. Sharing a sentence is not in itself a finding about the gene and the disease. The quoted sentences say what the papers report.
breast carcinoma (3 papers, 2020 to 2024). "Notably, considering the observed overexpression of WRNIP1 in the most common human cancer types, such as lung and breast cancers, our discoveries contribute to a deeper understanding of mechanisms cells employ to counteract TRCs." (PMID 38488661, 2024). "Furthermore, as WRNIP1 has been found overexpressed in the most common cancers worldwide, such as lung and breast cancers, WRNIP1 could be considered a potential target in cancer therapy." (PMID 32046194, 2020).
anemia (1 paper, 2020). A reduction in the number of red blood cells, the amount of hemoglobin, and/or the volume of packed red blood cells. "Many proteins participate in this protection including BRCA2, RAD51, WRNIP1, or Fanconi anemia proteins (37, 40, 43, –, 45)." (PMID 31757807, 2020).
clear cell renal carcinoma (1 paper, 2018). A malignant epithelial neoplasm of the kidney characterized by the presence of lipid-containing clear cells within a vascular network. "Also of interest were two variants in WRNIP1 that were predicted as damaging by all in silico tools, which occurred in the same individual, who had early onset cancers (thyroid cancer at 31, CM at 42 and multifocal clear cell renal cancer at 58 years of age." (PMID 29641532, 2018).
colon cancer (1 paper, 2023). "We expected that the transcription factors WRNIP1, ATF1, CBFB, and NR2F6, as well as the microRNAs miR-1-3p, miR-26b-5p, miR-164a-5p, and miR-9-5p, would play essential roles in metabolic abnormalities of cells in obese people and the development of colon cancer." (PMID 37711894, 2023).
lung carcinoma (1 paper, 2017). "WRNIP1 is involved in cell cycle progression, and its phosphorylation is reduced by FGFR1OP in lung cancer." (PMID 29052520, 2017).
retinoblastoma (1 paper, 2018). A malignant tumor that originates in the nuclear layer of the retina. "Stress response proteins that were identified to be hyperphosphorylated in retinoblastoma compared to control retina tissues included H2AFX, SIRT1, TNIK, WRNIP1, BAZ1B, and CDK1." (PMID 29914080, 2018).
cancer (7 papers, 2018 to 2024). A tumor composed of atypical neoplastic, often pleomorphic cells that invade other tissues. "Importantly, since a direct connection between R-loops and cancer has been recognised, WRNIP1 could be employed as a target to further sensitise cancer cells to inhibitors of ATR or CHK1 that are currently under clinical evaluation." (PMID 35163467, 2022). "MAGEC3 also upregulates a stress-related gene, WRNIP1, a DNA replication gene, MCM7, and cancer-related genes, XPO5 and ZSCAN16." (PMID 35158998, 2022). "Previous studies showed GLRX3, GLRX5, WRNIP1, THOP1, and HSCB were all regulators of various cancer occurrence and progression." (PMID 34078439, 2021). "Because elevated genome instability is caused by MRS after WRNIP1 depletion in cells with dysfunctional ATR checkpoint, these findings could contribute to understanding how cells handle replication–transcription conflicts to eventually avoid early-onset of human diseases and cancer." (PMID 32046194, 2020). "Expression of all the 23 target genes changed in HT1080 cells; 20 genes were up-regulated and two genes PDGFR β and WRNIP1 were down-regulated (OPN4 did not change significantly; PDGFR β decrease on TRF2 silencing in cancer cells was also noted earlier)." (PMID 30439955, 2018).
WRNIP1 also shares sentences with these, for which no sentence is quoted: thyroid cancer (1 paper); tumor (1).